ANGPTL4 (angiopoietin like 4)
Diseases named in the same sentence as ANGPTL4 in open-access papers (continued):
Sharing a sentence is not in itself a finding about the gene and the disease.
Impaired glucose tolerance (4 papers, 2020 to 2021). An abnormal resistance to glucose, i.e., a reduction in the ability to maintain glucose levels in the blood stream within normal limits following oral or intravenous administration of glucose. "Mice overexpressing ANGPTL4 reportedly show impaired glucose tolerance, and conversely, ANGPTL4-deficient mice show improved glucose tolerance." (PMID 34293055, 2021). "Moreover, ANGPTL4 was shown to be involved in glucose metabolism, although findings in this regard are not conclusive, as ANGPTL4 overexpression in mice has been associated to either improved or impaired glucose tolerance in different studies." (PMID 33003532, 2020). "Our findings are consistent with these researches that in VAT of triple-transgenic pigs with impaired glucose tolerance and heterogenic adipocytes, and ANGPTL4 mRNA level was increased, as well as VAT inflammation." (PMID 34322121, 2021). "For instance, serum ANGPTL4 levels were significantly higher in obese patients with impaired glucose tolerance than in lean healthy participants, and a positive correlation was observed between serum ANGPTL4 levels as well as BMI, waist circumference, fat mass, and triglyceride levels." (PMID 32277104, 2020).
lupus nephritis (4 papers, 2017 to 2024). Glomerulonephritis in the context of systemic lupus erythematosus. "Two patients with class II lupus nephritis in remission showed minimal staining for glomerular Angptl4." (PMID 28441404, 2017). "Interestingly, Angptl4 has been identified as a candidate biomarker for lupus nephritis in patients with SLE." (PMID 35210411, 2022). "Compared to controls, glomerular Angptl4 was overexpressed in kidney tissue from 2 MCD patients in remission, 5 patients with FSGS and proteinuria, 1 patient with class IV lupus nephritis during relapse and 1 MPGN patient during remission." (PMID 28441404, 2017).
pancreatitis (4 papers, 2020 to 2025). Inflammation of the pancreas. "Herein, we provide evidence that ANGPTL4 exacerbates pancreatitis and elucidate its underlying mechanisms of action." (PMID 32638512, 2020). "Since the upregulation of C5a by ANGPTL4 is associated with the severity of pancreatitis, we measured the levels of C5a in the sera of patients with pancreatitis and then evaluated the correlation between C5a and ANGPTL4." (PMID 32638512, 2020). "The deficiency in ANGPTL4 in mice, either by gene deletion or neutralizing antibody, mitigated pancreatitis‐associated pathological outcomes." (PMID 32638512, 2020). "The ANGPTL4 alone (4 mg/kg) group showed not only pathological changes associated with severe pancreatitis but also higher cytokine levels than those of the SAP group." (PMID 32638512, 2020). "The loss of ANGPTL4 in mice reduced inflammatory infiltration and cytokine levels, where pancreatitis pathological phenomena such as acinar cell necrosis and protease activation were very rare, suggesting that ANGPTL4 is a regulator in the progression of pancreatitis severity." (PMID 32638512, 2020). "To identify whether elevated plasma TG by ANGPTL4 is a key risk factor in pancreatitis, we evaluated TG levels in pancreatitis patients (n = 80) compared with those of normal subjects." (PMID 32638512, 2020). "Additionally, we confirmed that the AP+ANGPTL4 group exhibited pathological phenomena that were associated with severe pancreatitis together with high amylase and cytokine levels." (PMID 32638512, 2020). "Our findings suggest that targeting ANGPTL4 could be an effective treatment strategy to directly address the cellular causes of pancreatitis." (PMID 32638512, 2020). "Treatment of mice with severe and mild pancreatitis using an ANGPTL4-neutralizing antibody results in reduced C5a levels and significantly alleviates pathological features of pancreatitis." (PMID 40723247, 2025). "In this context, ANGPTL4 has been shown to induce pancreatitis in mouse models by upregulating complement component 5a (C5a) in macrophages via PI3K/AKT signaling." (PMID 40723247, 2025). "In conclusion, we showed that ANGPTL4 induced pancreatitis and was correlated with acute pancreatitis severity." (PMID 32638512, 2020). "For this experiment, we prepared bone marrow‐derived macrophages from pancreatitis‐induced ANGPTL4−/− and WT mice." (PMID 32638512, 2020). "Concurrently, a significant positive correlation between C5a and ANGPTL4 levels was observed in pancreatitis patients." (PMID 32638512, 2020). "On the other hand, pancreatitis conditions induced by ANGPTL4 were prominently reduced in macrophage‐depleted animal models." (PMID 32638512, 2020). "We found that C5a production was increased in macrophages from ANGPTL4 WT mice with pancreatitis (AP and SAP), whereas the level of C5a was reduced in macrophages from ANGPTL4−/− mice, compared with that in macrophages from ANGPTL4 WT mice." (PMID 32638512, 2020). "In this regard, our results verified that ANGPTL4 is a pivotal regulator that exacerbates the severity of pancreatitis via macrophage activation and migration." (PMID 32638512, 2020). "Considering the pathological role of ANGPTL4 in pancreatitis, we expected that targeting ANGPTL4 and C5a would reduce pancreatitis." (PMID 32638512, 2020). "To identify the biological significance of ANGPTL4 in a clinical situation, we first assessed ANGPTL4 expression in pancreatitis patients." (PMID 32638512, 2020). "There was little change in the level of PPAR‐γ according to the severity of pancreatitis as well as between ANGPTL4−/− and WT mice." (PMID 32638512, 2020). "In agreement, there was a significant positive correlation between C5a and ANGPTL4 levels in pancreatitis patients." (PMID 32638512, 2020). "A fourfold increase in ANGPTL4 levels was observed in the serum of pancreatitis patients, with increase in amylase, lipase, and CRP." (PMID 32638512, 2020).
pancreatitis (continued). "Targeting ANGPTL4 by a neutralizing antibody is shown to be an effective strategy for the treatment of pancreatitis in mice." (PMID 32638512, 2020). "Since vacuoles are known to accumulate in pancreatitis, we also detected acinar cell vacuolation in response to ANGPTL4 treatment using transmission electron microscopy (TEM)." (PMID 32638512, 2020). "The level of C5a in patient sera was 2.5‐fold higher than that of sera from normal subjects, and there was a significant positive correlation between C5a and ANGPTL4 levels in pancreatitis patients (R2 = 0.72, P < 0.001)." (PMID 32638512, 2020). "Taken together, our study suggests that targeting ANGPTL4 is a potential strategy for the treatment of pancreatitis." (PMID 32638512, 2020). "In this study, ANGPTL4 is a possible pathological mediator that induces pancreatitis and increases the inflammatory response by macrophages." (PMID 32638512, 2020). "Clinically, ANGPTL4 expression was also increased in the serum and pancreatic tissues of pancreatitis patients." (PMID 32638512, 2020). "Our study shows that ANGPTL4 induces macrophage‐secreted C5a, which leads to massive release of inflammatory cytokines, resulting in increased pancreatitis severity by injuring acinar cells." (PMID 32638512, 2020). "In the case of ANGPTL4‐induced pancreatitis models, the levels of these cytokines were higher than those of AP and SAP models." (PMID 32638512, 2020). "In this study, ANGPTL4 was selected as a target gene that has a gradual increase according to the severity of pancreatitis based on microarray analysis of AP and SAP models." (PMID 32638512, 2020). "Furthermore, ANGPTL4 exacerbates pancreatitis by augmenting acinar cell injury through upregulation of C5a." (PMID 34616362, 2021). "This study identifies ANGPTL4 as a potential pathological mediator that induces pancreatitis." (PMID 32638512, 2020). "Although ANGPTL4 plays a role in inflammation, its exact function and mechanism in the inflammatory response is context‐dependent and still remains largely undefined, specifically in pancreatitis." (PMID 32638512, 2020). "Additionally, neutralizing antibodies targeting ANGPTL4 and C5a improved pancreatitis and pathological change in vitro and in vivo." (PMID 32638512, 2020). "Because that ANGPTL4 expression was highly increased in pancreatitis, we hypothesized that ANGPTL4 affects pancreatic acinar cell injury." (PMID 32638512, 2020). "Interestingly, the ANGPTL4‐treated groups [AP+ANGPTL4 and ANGPTL4 alone (4 mg/kg)] showed a reduced pancreatitis severity in the macrophage‐depleted groups compared with that of the macrophage WT groups, with decreased amylase and lipase levels." (PMID 32638512, 2020). "ANGPTL4 expression increased concomitantly with the number of apoptotic acinar cells (TUNEL‐positive cells) and amylase levels, suggesting that ANGPTL4 is associated with the severity of pancreatitis." (PMID 32638512, 2020). "Furthermore, to identify the expression pattern of ANGPTL4 in pancreatitis, we investigated its expression at 2 h, day 1, and 3 days after the induction of AP and SAP in mice." (PMID 32638512, 2020). "Therefore, we considered that various cytokines and chemokines released during macrophage activation by ANGPTL4 influence acinar cell death and further pancreatitis." (PMID 32638512, 2020). "To address whether ANGPTL4 induces pancreatitis directly or indirectly by interacting with other factors, we used ANGPTL4−/− mice and assessed the role of ANGPTL4 in acute pancreatitis (AP and SAP)." (PMID 32638512, 2020). "In addition, the expression of ANGPTL4 and amylase was increased in the pancreatic tissues of pancreatitis patients compared with that of adjacent normal pancreatic tissues." (PMID 32638512, 2020). "Therefore, the correlation between macrophages and ANGPTL4 in pancreatitis was investigated." (PMID 32638512, 2020).
pancreatitis (continued). "Furthermore, C5a decreased gradually according to the severity of pancreatitis in macrophages from ANGPTL4−/− mice with AP and SAP, compared with that of WT mice, suggesting that ANGPTL4 increases C5a in macrophages, leading to increased severity of pancreatitis." (PMID 32638512, 2020). "Also, we also speculated that systemic ANGPTL4 increases macrophage infiltration into pancreas, which increase C5a, leading to hypercytokinemia or cytokine storm that accelerated pancreatitis severity." (PMID 32638512, 2020). "However, the association of PPAR‐γ and ANGPTL4 in pancreatitis has not been investigated." (PMID 32638512, 2020). "We determined multiorgan ANGPTL4 expression in AP and SAP models, and the expression of ANGPTL4 in the pancreas progressively increased according to severity of pancreatitis." (PMID 32638512, 2020). "Therefore, we investigated whether there was a change in the expression of ANGPTL4 in pancreatitis." (PMID 32638512, 2020). "Our study showed that ANGPTL4 induced macrophage activation and migration, and activated the C5a‐C5aR axis via PI3K/AKT signaling, resulting in pathological changes in pancreatitis." (PMID 32638512, 2020). "Lending support, pancreatitis did not develop well in macrophage‐depleted mice injected with recombinant ANGPTL4." (PMID 32638512, 2020). "Because ANGPTL4 was highly expressed in AP and SAP, and affected the induction of the pancreatitis response in acinar cells, we investigated whether ANGPTL4 induced pancreatitis." (PMID 32638512, 2020). "Specifically, ANGPTL4 did not exacerbate pancreatitis when macrophages were depleted, suggesting that ANGPTL4 plays a positive role in macrophages in pancreatitis progression." (PMID 32638512, 2020). "ANGPTL4 as well as cholecystokinin (CCK) or LPS, which are inducers of pancreatitis, was administrated to acinar cells, and we examined whether these factors directly affected the death of pancreatic acinar cells, leading to pancreatitis." (PMID 32638512, 2020).
polycystic ovary syndrome (4 papers, 2019 to 2025). A disorder that manifests as multiple cysts on the ovaries. "This study aims to characterize the expression of ANGPTL4 in ovarian granulosa cells (GCs) and its association with polycystic ovary syndrome (PCOS)." (PMID 35140683, 2021). "Angiopoietin like 4 (Angptl4) is an angiogenic factor and lipid metabolism regulator that has been characterized in cumulus cells and in cases of polycystic ovarian syndrome (PCOS)." (PMID 37157877, 2023).
renal fibrosis (4 papers, 2024 to 2025). A final common manifestation of a wide variety of chronic kidney diseases characterized by glomerulosclerosis and tubulointerstitial fibrosis. "Its impact on the progression of renal fibrosis was examined through the modulation of ANGPTL4 expression levels in vitro." (PMID 38992710, 2024). "Our findings indicate that ANGPTL4 is a key regulatory factor in renal fibrosis, forming a loop with HIF-1α, potentially serving as a novel therapeutic target for RIF." (PMID 38992710, 2024). "Analysis of diabetic kidneys from Angptl4 mutant mice shows suppression of renal fibrosis, proteinuria, pro-inflammatory cytokines, and mesenchymal activation in tubules and endothelial cells when compared to diabetic controls." (PMID 39630889, 2024). "Studies have shown that angiopoietin-like protein 4 (ANGPTL4) expression is significantly upregulated in CKD rats and patients, suggesting ANGPTL4 may be a novel noninvasive marker of renal fibrosis." (PMID 40809416, 2025). "Previous studies have identified ANGPTL4 and MDK as key factors in inducing CAFs transformation and mediating renal fibrosis." (PMID 41383622, 2025). "Therefore, in this study, we investigated the role of ANGPTL4 in the pathogenesis of RIF by establishing in vivo and in vitro renal fibrosis models complemented by validation in human fibrotic kidney tissues." (PMID 38992710, 2024). "To further investigate the interaction between DPP-4–Integrin β1 and Angptl4, we analyzed microRNA array data from nondiabetic mice and diabetic mice with severe renal fibrosis." (PMID 39630889, 2024). "However, there is currently a lack of pertinent research on whether ANGPTL4 influences renal fibrosis." (PMID 38992710, 2024). "Notably, following ANGPTL4 knockdown, the level of α-SMA remained greater than that in the control group, indicating that ANGPTL4 may not be the sole regulatory factor in renal fibrosis and that other HIF-1α-mediated regulatory pathways, such as the PI3K/AKT signaling pathway, may also be involved." (PMID 38992710, 2024).
arteriosclerosis (3 papers, 2018 to 2026). A vascular disorder characterized by thickening and hardening of the walls of the arteries. "Consequently, ANGPTL4 not only regulated TC by inhibiting LPL, but also affected serum lipid levels and arteriosclerosis by other pathways." (PMID 30323852, 2018).
cardiomyopathy (3 papers, 2007 to 2022). A disease of the heart muscle or myocardium proper. "Cardiac-restricted overexpression of ANGPTL4 in mouse model significantly inhibits cardiac LPL activity and results in cardiomyopathy." (PMID 34616362, 2021). "Interestingly, we showed a 5-fold increase in the level of Angptl4 transcript in the heart of iron-loaded mice, raising the possibility that early induction of Angptl4 expression could contribute to the pathogenesis of cardiomyopathy in HH." (PMID 17949489, 2007). "Transgenic mice with Angptl4 overexpression directed to heart muscle (lipoprotein-derived fatty acids are the major energy source in this tissue) show reduced cardiac LPL activity, decreased triglyceride utilization and impaired cardiac function resulting in cardiomyopathy." (PMID 17949489, 2007).
chronic hepatitis (3 papers, 2018 to 2025). An active inflammatory process affecting the liver for more than six months. "Previously, circulating levels of ANGPTL3 and ANGPTL4 were found to be elevated in HCC patients compared to those with chronic hepatitis and healthy individuals." (PMID 39708716, 2025). "Consistent with our observation, previous studies reported higher circulating ANGPTL4 levels in patients with HCC than in those with chronic hepatitis alone and healthy controls." (PMID 32695883, 2020). "ANGPTL4 expression was able to discriminate chronic hepatitis cases from controls and those HCC cases from chronic hepatitis patients." (PMID 29389861, 2018). "The chronic hepatitis secondary to viral or non-viral causes in addition to the presence of HCC likely contributed to the high circulating ANGPTL4 levels in our patient cohort." (PMID 32695883, 2020).
chronic kidney disease (3 papers, 2017 to 2023). Impairment of the renal function secondary to chronic kidney damage persisting for three or more months. "It is not unlikely that similarly to how ANGPTL2 and TGFβ1 positively increase the expression of each other in chronic kidney disease, ANGPTL4 and TGFβ1 employ such reciprocal effects on each other expression." (PMID 29100268, 2017). "Further, a clinical study reported that ANGPTL-4 was correlated with chronic kidney disease and may act as a universal marker of declining kidney function." (PMID 37108963, 2023).
Cirrhosis (3 papers, 2021 to 2024). A chronic disorder of the liver in which liver tissue becomes scarred and is partially replaced by regenerative nodules and fibrotic tissue resulting in loss of liver function. "ANGPTL-3 was decreased in patients with advanced fibrosis compared to other disease stages, while ANGPTL-4 was progressively increased from acute infection to cirrhosis and HCC, peaking at the advanced fibrosis stage." (PMID 34360721, 2021). "Additionally, ANGPTL4 has been shown to be significantly upregulated in patients with cirrhosis and in cellular models of liver injury induced by the hepatitis C virus." (PMID 38992710, 2024). "However, in opposition to ANGPTL-3, ANGPTL-4 levels peaked in the advanced fibrosis group, with a value of 102.8 ng/mL, and remained relatively high in the cirrhosis and HCC groups." (PMID 34360721, 2021). "Conversely, ANGPTL-4 displayed an increasing tendency from the early (acute infection/mild fibrosis) to late (cirrhosis/HCC) stages, but in a non-linear way since it peaked in patients with advanced fibrosis." (PMID 34360721, 2021). "Interestingly, both ANGPTL-3 and ANGPTL-4 serum levels did not statistically differ between the early stages of acute infection and mild fibrosis or the late stages cirrhosis and HCC." (PMID 34360721, 2021).
Cognitive impairment (3 papers, 2024 to 2025). Abnormal cognition is characterized by deficits in thinking, reasoning, or remembering. "The APOEε4-specific association of ANGPTL4 with future cognitive impairment may be driven by the joint role of ANGPTL4 and APOE in lipid metabolism." (PMID 39482741, 2024). "Experimental evidence indicates that in mouse models of acute ischemic stroke, ANGPTL4 promotes angiogenesis and neurogenesis, thereby facilitating the recovery of neurological function and cognitive impairment at the earliest possible stage." (PMID 40988927, 2025). "Inconsistent with the upregulation of ANGPTL4 in plasma among those at risk for cognitive impairment, autopsied AD brains (compared to non-AD control brains) showed reduced ANGPTL4 expression in astrocytes, neurons, cerebrovascular cell types, and meningeal fibroblast." (PMID 39482741, 2024). "ANGPTL4 is expected to be a biomarker for the early identification of WMH and cognitive impairment progression in CSVD patients." (PMID 39470400, 2024).
diabetic cardiomyopathy (3 papers, 2021 to 2026). Diabetic cardiomyopathy is a disorder of the heart muscle in people with diabetes. "Therefore, it can be speculated that ANGPTL4 may regulate the cell communication (exp: increased of FA) of ECs-CMs caused by hyperglycemia and become a potential therapeutic target for diabetic cardiomyopathy by regulating lipid metabolism and glucose metabolism." (PMID 40296165, 2025). "Finally, ANGPTL4, a key mediator of senescence in diabetic cardiomyopathy, exhibits dual roles." (PMID 41522514, 2026).